PPP2R3A (protein phosphatase 2 regulatory subunit B''alpha)
Diseases named in the same sentence as PPP2R3A in open-access papers (continued):
Sharing a sentence is not in itself a finding about the gene and the disease.
tumor (15 papers, 2013 to 2025). "In addition, we analyzed the expression of PPP2R3A in clinical human pancreatic cancer tissue samples and found that upregulation of PPP2R3A expression was significantly associated with tumor recurrence." (PMID 37124502, 2023). "Among them, PPP2R3A was implicated as a tumor-suppressor gene contributing to cell transformation." (PMID 24564330, 2013). "We found that PPP2R3A protein expression was higher in tumor tissues than in adjacent para‐tumor tissues of HCC patients." (PMID 31647192, 2019). "In a xenograft cancer model in nude mice, the in vivo effects of PPP2R3A knockdown on tumor growth and cancer cell proliferation were evaluated." (PMID 31647192, 2019). "Western blotting analysis of the tissue lysates also showed a higher expression level of PPP2R3A in tumor foci than in the adjacent para‐tumor tissues in six of eight HCC patients, which was consistent with the results of immunohistochemical analysis." (PMID 31647192, 2019). "Overall, these results suggest that PPP2R3A is a tumor-promoting factor in pancreatic cancer." (PMID 37124502, 2023). "Importantly, wound healing assays and transwell results demonstrated that tumor cell migration and invasion were also significantly reduced after PPP2R3A knockdown." (PMID 37124502, 2023). "Furthermore, knockdown of PPP2R3A in AsPC-1 cells significantly inhibited xenograft tumor growth in mouse models." (PMID 37124502, 2023). "Protein phosphatase 2A regulatory subunit B ′′α (PPP2R3A) regulates the cell cycle mainly by targeting cell cycle regulators and apoptosis factors and has attracted attention due to its involvement in the regulation and development of tumor signaling pathways." (PMID 35933397, 2022). "In contrast, PART1 knockdown upregulated PPP2R3A, which is a suspected tumor suppressor." (PMID 34072264, 2021). "The PPP2R3A may play a pro‐tumor function in HCC by regulating the proliferation and invasion of HCC cells." (PMID 31647192, 2019). "Studies have shown that PPP2R3A mainly regulates the cell cycle by targeting cell cycle regulators and apoptosis inhibitors, and this molecule has received extensive attention due to its involvement in the regulation of important tumor signaling pathways, developmental processes and the cell cycle." (PMID 35933397, 2022). "PPP2R3A expression was found in tumor foci in six of eight HCC samples, at a level higher than that in the adjacent para‐tumor tissues." (PMID 31647192, 2019). "Promoter methylation analysis revealed that PPP2R2B, and to some extent PPP2R3A and PPP2R5A are the only subunits predominantly methylated across multiple tumor types." (PMID 27557495, 2016). "Our results demonstrate that PPP2R3A is highly expressed in the HRS group and in C1, suggesting that this protein may be a tumor-promoting factor." (PMID 37124502, 2023). "PPP2R3A knockdown (shRNA1 or shRNA2) in Huh‐7 cells significantly slowed the tumor growth in vivo, compared with that seen in the negative control group (P < .001)." (PMID 31647192, 2019). "Positive PPP2R3A expression was found in HCC cells in six of eight specimens, while negative or very low‐level PPP2R3A expression was observed in the liver cells in the adjacent para‐tumor tissues." (PMID 31647192, 2019). "Moreover, PPP2R3A protein expression was high in HCC tissues, but not in the adjacent para‐tumor tissues." (PMID 31647192, 2019).
cancer (14 papers, 2013 to 2025). A tumor composed of atypical neoplastic, often pleomorphic cells that invade other tissues. "Although a positive role for the PP2A B”α/PR130 subunit (encoded by PPP2R3A) has been inferred in cancer cell migration, the role of the related B”γ/G5PR subunit (encoded by PPP2R3C) in migration or EMT induction remains unclear." (PMID 37170215, 2023). "A recent work analyzed Cancer-Genome-Atlas (TCGA) datasets and surgically removed human PDACs for a link between the PPP2R3A mRNA expression and PR130 with patient survival." (PMID 38570831, 2024). "Protein phosphatase 2 regulatory subunit B alpha (PPP2R3A) regulates several important signal transduction pathways related to cancer including the Wnt signaling cascade, adenosine monophosphate‐activated protein kinase activity, and epidermal growth factor (EGF)/EGF receptor signaling pathway." (PMID 35128835, 2022). "PPP2R3A expression was observed primarily in the cytoplasm of the cancer cells." (PMID 31647192, 2019). "PPP2R3A was highly expressed in the high-risk group, indicating that these genes may be related to the oncology process for patients with PAAD, and they seemed to be cancer-promoting genes." (PMID 39655212, 2024). "MET, AM25C, MROH9, MYEOV, FAM111B, Y6D, and PPP2R3A were highly expressed in the high-risk group, indicating that these genes may be related to the oncology process for patients with PAAD, and they seemed to be cancer-promoting genes." (PMID 35077391, 2022). "In addition, the positive staining of PPP2R3A was detected mainly in the cytoplasm of HCC cells and sporadically in the endothelial cells in the stroma adjacent to cancer lesions." (PMID 31647192, 2019). "Those pathways specifically altered in primary tumors were associated with an abnormally increased expression of genes that are involved in focal adhesion (e.g., PRKCA, CRK, and BCL2), PI3K-Akt signaling (e.g., PHLPP2, PRKCA, PPP2R3A and KIT) and cancer pathways (e.g., COL4A5, LAMC1 and BCL2L1)." (PMID 27662660, 2016).
heart diseases (1 paper, 2023). "But not only do the candidate genes that interact with PPP2R3A show altered expression in common heart diseases, but PR72 itself also exhibits changes in expression." (PMID 37868783, 2023).
infection (1 paper, 2019). The state of being infected such as from the introduction of a foreign agent such as serum, vaccine, antigenic substance or organism. "Specifically, after infection with shRNA1 or shRNA2 for PPP2R3A knockdown, the numbers of migrating Huh‐7 cells decreased by 80.5%±11.0% and 75.4%±7.6%, respectively, and the numbers of migrating HepG2 cells decreased by 63.5%±16.5% and 48.0%±10.1%, respectively." (PMID 31647192, 2019).
PPP2R3A also shares sentences with these, for which no sentence is quoted: colorectal cancer (3 papers); acute lymphoblastic leukemia (2); fibrosarcoma (2); lung carcinoma (2); breast carcinoma (1); cardiac hypertrophy (1); cardiomyopathy (1); COVID-19 (1); gastric cancer (1); hyperlipidemia (1); leprosy (1); melanoma (1); myocardial infarction (1); pancreatic adenocarcinoma (1); pancreatic ductal adenocarcinoma (1); viral infection (1).